BRCA2 (BRCA2 DNA repair associated)
Diseases named in the same sentence as BRCA2 in open-access papers (continued):
Sharing a sentence is not in itself a finding about the gene and the disease.
breast cancer (continued). "In fact, MDA-MB-468 cells had the highest level of BRCA2 expression among breast cancer cells and did not respond to siBRCA2, even though the other cell lines did respond." (PMID 27630665, 2016). "We and others have reported that the breast cancer risk fraction contributed by missense variants in BRCA1, BRCA2, ATM and CHEK2 is as high, if not higher, than protein-truncating variants in these genes." (PMID 27099641, 2016). "Therefore, we screened germline VNTR polymorphisms in the XRCC5 promoter in three types of familial breast cancer (BRCA1+, BRCA2+, and BRCAx)." (PMID 27148484, 2016). "Similarly, we previously reported on the prognostic significance of the combined expression patterns of the DDR molecules PARP1, γH2AX, BRCA1, and BRCA2 designated as CSbbph (combined score for the BRCA1, BRCA2, PARP1, and γH2AX) in breast carcinoma." (PMID 27643881, 2016). "Breast carcinoma in the CSbbph-low group that corresponds to a CSddrm-low immunophenotype has a 95% 10-year rate, but the ten-year DSS rate of breast carcinoma with a BRCA1+/BRCA2+/PARP1+/γH2AX+ immunophenotype was 35%." (PMID 27643881, 2016). "About 74% of BRCA1-related breast carcinomas, 23% of BRCA2-related breast carcinomas and 13% of sporadic breast carcinomas had triple negative phenotype lacking ER, PgR and HER2 expression (p < 0.001)." (PMID 27566577, 2016). "Genetics report 2 (from a female breast cancer patient with negative family history) was summarised as: “Heterozygous for BRCA2 c.9098C > T”." (PMID 26608569, 2015). "About 51% of the students with a family history of breast cancer and 20% with no family history of breast cancer had BRCA1 and BRCA2 mutations." (PMID 25641872, 2015). "Of a total 131 breast cancer sera analyzed, 15.3% (20/131) was shown to have autoantibody to PARP1, 19.1% (25/131) was shown to have autoantibody to BRCA1, 36.6% (48/131) was shown to BRCA2." (PMID 25865228, 2015). "In this study, we screened the mutations on the entire coding sequence of the CHEK2 gene by direct sequencing on a cohort of Asian high-risk breast cancer patients who have been tested negative for BRCA1 and BRCA2 gene mutations." (PMID 25629968, 2015). "Intriguingly, the same HMMR variation as originally detected in the Ashkenazi Jewish population was suggested to be associated with breast cancer risk in BRCA1, but not in BRCA2 mutation carriers." (PMID 25830658, 2015). "In the present study we employed whole-exome sequencing of seven cases diagnosed with familial breast cancer and with unknown BRCA1 or BRCA2 status." (PMID 25923920, 2015). "It has been detected in 5% of breast cancer patients from non-BRCA1 and BRCA2 families." (PMID 25674498, 2015). "The majority of hereditary OC (HOC) cases are also associated with an increased risk of breast cancer (BC) and the most frequent pathogenic mutations in hereditary breast and/or ovarian (HBOC) cancer families affect the BRCA1 gene and to a lesser extent also BRCA2." (PMID 26057125, 2015). "The genetic background in families with hereditary breast cancer without predisposing germ line mutations in BRCA1 and BRCA2 (non-BRCA families) is still to a large extent unclear even though progress has been made." (PMID 26082817, 2015). "We showed that the median age at diagnosis for TNBC patients with either BRCA1 or BRCA2 is younger than for non-TNBC patients (38 vs 46 for BRCA1 and 38.5 vs 48 for BRCA2), suggesting that BRCA1- and BRCA2-associated breast cancer is most likely early-onset." (PMID 26221963, 2015). "The PALB2 p.G998E variant in this patient was reported at a similar frequency of ~ 10% in a population of BRCA1- and BRCA2-negative male breast cancer patients in Northern Italy as was observed in healthy individuals." (PMID 26485759, 2015).
breast cancer (continued). "Despite intense research, GWAS and next generation sequencing (NGS) exome studies have not identified additional major breast cancer susceptibility genes, such as BRCA1 and BRCA2." (PMID 25360583, 2014). "Large genomic rearrangements have been characterized in BRCA1 and BRCA2 genes in several populations but these have not been characterized in Sri Lankan breast cancer patients." (PMID 24906410, 2014). "Our main analyses of breast tumor features included up to 3,929 BRCA1 mutation carriers, 2,273 BRCA2 mutation carriers, and 42,623 assumed BRCA1 and BRCA2 mutation-negative breast cancer cases." (PMID 25857409, 2014). "Overall, 15 breast cancer susceptibility variants were associated with ER-negative breast cancer in BRCA1 carriers and 8 variants in BRCA2 carriers at P <0.05." (PMID 25919761, 2014). "The high frequency of epigenetic silencing in BRCA1, BRCA2, and p14 suggests a potential influence of the virus on the methylation machinery, an oncogenic mechanism reported in other cancers but not yet in breast cancer." (PMID 24607238, 2014). "According to the findings of the present study BRCA1 and BRCA2 large genomic rearrangements are unlikely to significantly contribute to breast cancer in Sri Lanka." (PMID 24906410, 2014). "While most cases of breast cancers occur in women without a family history, about 10% of cases are found in women with mutations in BRCA1 or BRCA2 genes." (PMID 24523856, 2014). "Initial reports of comprehensive screening of all of the protein encoding exons of PALB2, identified no variants in 38 breast cancer families, where 22 families had a prior probability of greater than 10% of harboring a BRCA1 or BRCA2 mutation." (PMID 23302520, 2013). "Despite germ-line mutations in BRCA1 can account for a significant fraction of familial breast cancer cases, a large proportion of familial breast cancer are not related to mutations in BRCA1 or BRCA2." (PMID 23405268, 2013). "In the present study we used massively parallel sequencing to analyze 7 BRCA1/BRCA2 negative families, each having at least 6 affected women with breast cancer (between 6 and 10) diagnosed under the age of 60 across generations." (PMID 23409019, 2013). "Furthermore, a three-gene expression signature (BRCA2, DNMTB3, and CCNEI) was found to be an independent prognostic marker in breast cancer." (PMID 24289229, 2013). "A missense alteration, p.R361Q, resulting in abnormal DNA response, was identified in 3 out of the 125 Finish, BRCA1 and BRCA2 negative, families and one out of the 991 unselected breast cancer cases studied." (PMID 23586058, 2013). "Four PALB2 p.Q775X positive cases were also identified in a subsequent study involving 564 (0.7%) breast cancer cases not selected for family history of cancer, which also showed that 6% of cases harbored common BRCA1, BRCA2 or CHEK2 mutations." (PMID 23302520, 2013). "All patients had no family history of breast cancer, tested negative for BRCA1 and BRCA2, and had no other known breast cancer risks." (PMID 24151509, 2013). "Current findings suggest that the interactions between breast cancer susceptibility SNPs and breast cancer risk are not as strong as those for BRCA1 or BRCA2 gene mutation." (PMID 24289300, 2013). "BRCA2-related tumours usually express estrogen and progesterone receptors and tend to have similar features to sporadic breast cancers, unlike BRCA1-related cancers." (PMID 23586058, 2013).
breast cancer (continued). "In this study we have also identified 19 BRCA1 and 3 BRCA2 VUS that were predicted to alter known in vitro and in vivo phosphorylated sites, however, not yet characterized for their biological role in protein function or in breast cancer development." (PMID 23704879, 2013). "Another study showed also lack of association of the rs2910164 SNP with breast cancer risk in a series of BRCA1 and BRCA2 mutation carriers." (PMID 23586049, 2013). "Here we report that ever having breastfed and the total duration of breastfeeding conferred substantial reductions in breast cancer risk among BRCA1, but not BRCA2 mutation carriers." (PMID 22405187, 2012). "Analysis by tumour ER-status revealed that rs10771399 at 12p11 has a stronger association with ER-negative than ER-positive breast cancer for both BRCA1 and BRCA2 mutation carriers." (PMID 22348646, 2012). "We present results which highlight that contralateral breast cancer risk in women from BRCA1/2 negative families depends on age at onset of first breast cancer, as is the case for women from BRCA1 or BRCA2 positive families." (PMID 23216834, 2012). "In 77 TNBC cases from the United States that were not selected for age or familial breast cancer occurrence, the mutation frequencies were 15.6% for BRCA1 (n = 12) and 3.9% for BRCA2 (n = 3)." (PMID 22666503, 2012). "GWAS in the general population have recently identified eight additional breast cancer susceptibility loci which have not been previously investigated in BRCA1 and BRCA2 mutation carriers." (PMID 22348646, 2012). "For women who had their first breast cancer before the age of 40 years, the cumulative risk of contralateral breast cancer after 25 years was 55.1% for BRCA1, 38.4% for BRCA2, and 28.4% for patients from BRCA1/2 negative families." (PMID 23216834, 2012). "Canine mammary tumors are good models for human breast cancer, but the specific worth of canine BRCA2 has not been evaluated." (PMID 23071527, 2012). "Two (25%) BRCA2 mutations and no BRCA1 mutation were reported among eight male breast cancer patients in a small study." (PMID 22382806, 2012). "Here we report our analysis of RAD51D in 175 ovarian and breast cancer pedigrees, having at least one case of ovarian cancer in which BRCA1 and BRCA2 mutations were previously ruled out." (PMID 22415235, 2012). "Overall mutation of BRCA1 and BRCA2 genes in high-risk breast cancer patients without family history of breast or ovarian cancer in this study was 8.6% (BRCA1: 3.3%, BRCA2: 5.3%)." (PMID 22382806, 2012). "The present study evaluated the prevalence of BRCA1 and BRCA2 mutations in the second KOHBRA group, breast cancer patients without family history of breast or ovarian cancer with other risk factors for genetic predisposition." (PMID 22382806, 2012). "We found that among women diagnosed with breast cancer aged 36 to 50 years but with no family history of breast or ovarian cancer, the prevalence of BRCA1 and BRCA2 mutations was similar in TNBC (8.5%) and non-TNBC patients (6.7%)." (PMID 23116406, 2012). "In the case of the Triple-Negative derived BRCA1/BRCA2-deficient breast cancers, poly(ADP-ribose) polymerase (PARP), with or without DNA damaging agents, is synthetic lethal with BRCA1- or BRCA2-deficiency." (PMID 22363779, 2012). "In a Canadian TNBC cohort (n = 54) with an age of onset before 41 years and no familial breast cancer aggregation, five cases with mutations of BRCA1 (9%) and only one case with a mutation of BRCA2 (2%) were detected." (PMID 22666503, 2012). "Previously, we reported the first Hong Kong multi-center study that comprised of 119 breast cancer patients from this region to screen for coding sequence changes in the BRCA1 and BRCA2 genes using conventional full gene DNA sequencing and identified a recurrent mutation c.3109C>T." (PMID 22970155, 2012).
breast cancer (continued). "The KRAS variant allele was detected in 17.2% of sporadic breast cancer cases and in 18.2% of all familial cases (10.3% of BRCA carriers - 10.0% of BRCA1 and 11.1% of BRCA2 carriers and in 19.9% of non-BRCA carriers)." (PMID 22436609, 2012). "We have previously reported in a study of 965 matched pairs that the total duration of breastfeeding was associated with a significant reduction in breast cancer risk among BRCA1, but not among BRCA2, mutation carriers." (PMID 22405187, 2012). "Additionally several of the non-synonymous SNVs (66 in total) were present in genes with a previously established connection to breast cancer development through inherited genetic variations such as BRCA1 (seven SNVs) and BRCA2 (two SNVs)." (PMID 21698250, 2011). "In the group of families with no ovarian cancer but at least two or more breast cancer cases with only one of them diagnosed before the age of 50 (Group C), the mutation detection rate for BRCA1 was 11% and for BRCA2 8% or 19% for both genes." (PMID 21232165, 2011). "Recent GWAS have identified several other common breast cancer susceptibility variants which have not been investigated in BRCA1 and BRCA2 mutation carriers yet." (PMID 22053997, 2011). "As expected, the BRCA2 locus at 13q13.1 was not represented within the genetic networks constructed by using the same approach for sporadic breast cancers." (PMID 21958427, 2011). "This subtype of breast cancer is more common among BRCA1 gene mutation carriers, however, known BRCA1 and BRCA2 mutations do not seem to explain the triple negative cancer in Indian women." (PMID 20459777, 2010). "Although many women with BRCA mutations have a high probability of developing breast cancer, 15% of BRCA1-positive women and 20% of BRCA2-positive women will never develop breast cancer." (PMID 21037853, 2010). "Twenty-nine of the 138 patients with ER+ sporadic breast cancers (21%) had undergone genetic testing at BIDMC and none was found to have a BRCA1 or BRCA2 mutation." (PMID 20149218, 2010). "First-degree relatives of women with very early-onset breast cancer are at increased risk of cancers not explained by BRCA1 and BRCA2 mutations." (PMID 20877337, 2010). "The age-standardized incidence rate of breast cancer diagnosis was estimated to be 26.94 per 1,000 per year in BRCA1 carriers (95% confidence interval (CI) = 19.79, 34.10) compared with 25.03 per 1,000 per year in BRCA2 carriers (95% CI = 18.71, 31.36)." (PMID 19843326, 2009). "We therefore performed a study of hypoxic factors in BRCA1, BRCA2 and BRCAX breast cancers." (PMID 19724277, 2009). "In this study, we estimate the breast cancer risks for women with a strong family history of breast cancer, but tested negative for a mutation in BRCA1 or BRCA2." (PMID 19088722, 2009). "In this prospective study, we estimate breast cancer risks in women with a family history of breast cancer and for whom the proband tested negative for a mutation in BRCA1 or BRCA2." (PMID 19088722, 2009). "Families with two or more breast cancers under the age of 50 years, or with three cases of breast cancer at any age, and who tested negative for a BRCA1 or BRCA2 mutation were identified." (PMID 19088722, 2009). "The differences in age of diagnosis of breast cancer in the BRCA1 and BRCA2 mutation-positive groups did not permit the combined analysis of these groups versus mutation-negative group." (PMID 18402691, 2008).
breast cancer (continued). "Although there were differences in the ages of diagnosis of breast cancer in homozygous carriers of the 72Pro allele in BRCA1 and BRCA2 mutation positive groups, the mean age of diagnoses were not significantly different." (PMID 18402691, 2008). "We examined the mutation frequency of BRCA1, BRCA2, CHEK2 and ATM in women who had developed a second primary breast tumour at least 1 year after a first breast cancer diagnosed before the age of 50 years, with or without RT for their first breast cancer." (PMID 17428320, 2007). "According to the Breast Cancer Information Core (BIC) database, the majority of germline alterations identified in BRCA1 and BRCA2 is unique (57% and 63%, respectively); the remaining ones are recurrent founder mutations which have been described in different ethnic groups and populations." (PMID 17640379, 2007). "Both scenarios would explain the unsuccessful attempts to identify other breast cancer predisposition genes different from BRCA1 and BRCA2, due to lack of power." (PMID 17760956, 2007). "Several studies, using a variety of designs, have investigated the effect of parity on breast cancer risk among BRCA1 and BRCA2 mutation carriers, but the results have not been consistent." (PMID 17187672, 2006). "In other words, women with an altered BRCA1 or BRCA2 gene are 3 to 7 times more likely to develop breast cancer than women without alterations in those genes, with very high relative risks for early disease onset (before age 40) of about 30-fold." (PMID 17018160, 2006). "It takes into account the simultaneous effects of BRCA1, BRCA2 and the residual familial clustering of breast cancer not accounted by these genes, which is assumed to be explained by a polygenic model." (PMID 16417652, 2006). "The large majority of data accumulated so far indicates that, unlike what reported for female breast cancer (FBC), MBC is mainly linked to BRCA2 gene mutations." (PMID 16764716, 2006). "For instance, BRCA1 breast cancers are most often ER and PR negative, but BRCA2 cancers more often tend to be positive for these receptors." (PMID 15714204, 2005). "The identification of the TSG on 8p is an active research area in many laboratories, and linkage studies in some breast cancer families that do not have BRCA1 and BRCA2 mutations suggest that 8p12-22 is a candidate region." (PMID 16457686, 2005). "To date, both genetic and non-genetic factors have been suggested to influence breast cancer risk in BRCA1 and BRCA2 mutation carriers, and many implicate estrogen-induced stimulation as a probable contributor." (PMID 16168130, 2005). "A significantly increased risk of breast, prostate, cervical, and non-melanoma skin cancer was recently reported in first-degree relatives of early-onset breast cancer patients from Sweden that tested negative for BRCA1 and BRCA2 mutations." (PMID 15630470, 2004). "The International Breast Cancer Linkage Consortium data show that, among families with multiple cases of breast cancer but no known ovarian cancers, BRCA1 and BRCA2 mutations are almost equally represented." (PMID 12698193, 2003). "It is clear from studies by the Breast Cancer Linkage Consortium that BRCA1 and BRCA2 mutations do not account for all multi-case breast cancer families." (PMID 11875732, 2002). "The existing genetic models are either based on a single susceptibility gene or take into account only the effects of BRCA1 and BRCA2 and hence they do not describe the familial breast cancer adequately." (PMID 11857015, 2002). "In conclusion, the present results suggest that a number of low penetrant genes may account for the familial clustering of breast cancer outside BRCA1 and BRCA2 families." (PMID 11857015, 2002). "The missense changes occurred in a small region of the BRCA2 gene (from position 6443 to 6612) within 169 base pairs of one another and were all identified in patients with breast cancer and not in 100 control subjects." (PMID 12373604, 2002).